INS (insulin)
Diseases named in the same sentence as INS in open-access papers (continued):
Sharing a sentence is not in itself a finding about the gene and the disease.
Hyperglycemia (continued). "However, it is likely multifactorial, potentially involving impairments in both glucose disposal and insulin secretion, stress hyperglycemia, the unmasking of pre-existing undiagnosed diabetes, and steroid-induced hyperglycemia." (PMID 41441037, 2025). "There are also some reports of glycogenic hepatopathy occurring in patients with post-gastric bypass dumping syndrome, short-term high-dose corticosteroid therapy, and insulin overdose, whose mechanism of disease also involves hyperglycemia and hyperinsulinemia." (PMID 40757798, 2025). "The preprandial hyperglycemia correction dose was based on a table with three columns (insulin-sensitive, usual, and insulin-resistant), which could be adjusted according to the researcher’s decision." (PMID 39939862, 2025). "Consequently, Dityr disrupts TH-mediated transcriptional regulation, specifically impairing T3-dependent insulin synthesis and secretion, contributing to hyperglycemia." (PMID 41008194, 2025). "These alterations contribute directly to the development of hyperglycemia, followed by pancreatic β-cells increasing insulin secretion impaired insulin signaling in skeletal muscle, which results in chronic hyperinsulinemia, culminating in the development of type 2 DM." (PMID 40863135, 2025). "Given the lack of inpatient trials specifically focusing on SGLT2is for hyperglycemia management and given ample data supporting the safe use of basal-bolus insulin or DPP4is, current guidelines advise against using SGLT2is for managing hyperglycemia in hospital settings." (PMID 39816910, 2025). "However, achieving optimal control in insulin-dependent states remains challenging owing to the wide fluctuations in glucose levels, including hypoglycemia and hyperglycemia." (PMID 40932945, 2025). "Another effect of exercise is an increase in insulin sensitivity and protection from hyperglycemia." (PMID 40429969, 2025). "Due to the lack of insulin, T1D patients experience hyperglycemia, which can cause severe complications such as heart disease, stroke, nerve damage, and kidney failure." (PMID 40904460, 2025). "Collectively, these findings validate a central role for cAMP in mediating incretin signaling, but also demonstrate broad impairment of insulin secretion in the absence of Gαs that causes both fasting hyperglycemia and glucose intolerance." (PMID 40526441, 2025). "Alternative options to control hyperglycemia include insulin pumps, which may help reduce hypoglycemic events." (PMID 40144769, 2025). "Furthermore, HYA ameliorated postprandial hyperglycemia in type 1 diabetes model rats injected with bolus insulin immediately before OGTT." (PMID 39899133, 2025). "EKA typically arises when insulin levels are relatively low, but not enough to cause hyperglycemia, resulting in unchecked lipolysis and ketogenesis." (PMID 40443633, 2025). "This study was then undertaken to examine the contribution and the interconnection of hyperglycaemia, insulinopenia, IR and oxidative stress to bone fragility, as well as the time- and severity-dependent effects of insulin impairment on bone fragility and its reversibility." (PMID 41194975, 2025). "Therefore, we cannot exclude the possible contribution of altered insulin dynamics to the observed postprandial hyperglycemia." (PMID 41009421, 2025). "In another study, induction of chronic stress for 28 days could evoke insulin insensitivity and hyperglycemia through down-regulation of GLUT4 levels in skeletal muscles." (PMID 40656624, 2025). "HYA also ameliorated the postprandial hyperglycemia in T1DM rats given bolus insulin." (PMID 39899133, 2025). "Additionally, Bai (25 mg/kg/d and 50 mg/kg/d) and GALR2 antagonist M871 (10 mg/kg/d) improved metabolic function in obese mice by reducing hyperglycemia and enhancing insulin sensitivity." (PMID 41044789, 2025).
Hyperglycemia (continued). "Importantly, Jak2 deficiency in myeloid cells prevented HFD-induced hyperinsulinemia and hyperglycemia and improved both insulin and glucose tolerance as compared with that of HFD-fed Jak2+/+ mice." (PMID 40801626, 2025). "However, compared to repaglinide, nateglinide has an even faster onset and shorter duration of action, leading to a more pronounced early-phase insulin release, which is particularly effective in attenuating postprandial hyperglycemia." (PMID 41011221, 2025). "As outlined in the trendlines of standard CMD and Loke MD, glucose levels increased in response to induced hyperglycemia, decreased after insulin treatment, decreased further during intracranial hypertension, and increased again after another episode of hyperglycemia." (PMID 39085507, 2025). "Although insulin secretion was significantly higher from minutes 20 to 60 postoperatively, it returned to basal levels approximately 2 hours earlier, limiting systemic exposure to hyperinsulinemia and hyperglycemia." (PMID 39911520, 2025). "However, a notable and clinically relevant side effect of PI3Ki is the occurrence of hyperglycemia, which arises due to the disruption of insulin signaling pathways." (PMID 40573322, 2025). "In pancreatic β cells, cadherin-mediated adherens junctions are involved in insulin secretion and may be disrupted by hyperglycemia, contributing to diabetic complications." (PMID 41011980, 2025). "Athletes mentioned increasing basal insulin before a competition to prevent hyperglycemia." (PMID 39823464, 2025). "This reduction was accompanied by improved glycemic control, with a decrease in time spent in hyperglycemia and an increase in time in the target range (70–180 mg/dL), suggesting acute and chronic improvements in insulin sensitivity due to the increased glucose utilization induced by exercise." (PMID 40407447, 2025). "We may conclude that the emerging hyperglycaemia is a result of a deficit in insulin action, resulting in diminished postprandial glucose utilisation by the mother." (PMID 39861104, 2025). "There are many physiological components involved in preterm hyperglycaemia including exogenous glucose load, persistent inappropriate endogenous glucose production, stress response, reduced insulin production secondary to β-cell repopulation, immaturity, and insulin insensitivity." (PMID 41149637, 2025). "This narrative review aims to present the different mechanisms in which carbohydrate, protein, and fat influence postprandial hyperglycemia, reviewing recent published knowledge on the glycemic impact of high-fat and high-protein meals, as well as the required insulin doses and adjustments." (PMID 41462804, 2025). "The concern with people on insulin pump therapy is they do not usually take any long‐acting insulin so if there is any interruption to insulin delivery (e.g. if the cannula is blocked or dislodged), hyperglycaemia and then ketoacidosis can develop very quickly." (PMID 39432570, 2025). "Moreover, our data illustrate that while Gαs-independent pathways contribute to insulin secretion, this action is insufficient to correct hyperglycemia or mediate the full response to incretin receptor agonists." (PMID 40526441, 2025). "As detailed below, however, the inability to secrete insulin, due for example to β cell injury, in combination with brain-driven fuel mobilization, creates a vicious cycle fundamental to the pathogenesis of uncontrolled hyperglycemia and DKA." (PMID 40759579, 2025). "The patients were required to be aged over 18 years old and to be undergoing treatment for hyperglycemia, whether with metformin, other oral antidiabetic drugs, or insulin." (PMID 39931619, 2025). "Hyperglycemia is an adverse effect of steroids and is managed with insulin." (PMID 38470507, 2025).
Hyperglycemia (continued). "However, strategies to control hyperglycemia by elevating glucose uptake (insulin, thiazolidinediones, and biguanides) or augmenting the production of the net insulin (sulfonylureas) have shown limited benefits." (PMID 38204223, 2025). "Hyperglycemia increases the demand for insulin production, leading to excessive protein synthesis." (PMID 40534855, 2025). "According to the literature, reduced time in hyperglycemia may result from enhanced insulin action in muscle and liver, which can be modified by acute and regular bouts of exercise." (PMID 40407447, 2025). "Vitamin K shows protective effects against hyperglycemia and may enhance insulin secretion and β-cell proliferation in T1D animal models." (PMID 41156550, 2025). "In the immediate post-transplant period (typically within the first 6 weeks), insulin is often the preferred therapy to rapidly control hyperglycemia and provide β-cell rest, a strategy that may help reduce the risk of persistent dysglycemia." (PMID 40995094, 2025). "Unlike healthy horses, which typically maintain stable glucose homeostasis through effective insulin regulation, EMS-affected individuals experience insulin dysregulation, leading to persistent hyperglycemia and an increased risk of laminitis and other metabolic complications." (PMID 40941322, 2025). "This may be because FPG primarily reflects basal metabolic status, while concurrent skeletal muscle insulin resistance leads to sustained maternal hyperglycemia, prolonging fetal exposure to elevated plasma glucose levels." (PMID 40375950, 2025). "Pro-inflammatory immune cells and their cytokines, such as TNF-α and IL-6, impair adipose function and induce systemic insulin resistance; secondary hyperglycemia and metabolic disturbances, such as AGEs accumulation, then exacerbate periodontal immuno-stress and destruction." (PMID 41246338, 2025). "Indeed, CCL4 inhibition has demonstrated benefits in reducing hyperglycemia progression and improving insulin sensitivity." (PMID 41030257, 2025). "Similarly, stress-induced hyperglycemia observed in systemic infections reflects cytokine-driven insulin resistance and increased gluconeogenesis." (PMID 40792110, 2025). "Although compensatory insulin secretion increases, it is insufficient to effectively lower blood glucose levels or may even fail to prevent hyperglycemia." (PMID 41487501, 2025). "Previous studies have reported similar outcomes, where B12 improved metabolic parameters without fully normalizing hyperglycemia in insulin-deficient models." (PMID 41463345, 2025). "Hyperglycaemia, a well-known risk factor for ICU-acquired weakness (ICUAW), and its treatment with insulin may disrupt neuronal and muscle cell homeostasis by affecting mitochondrial function and autophagy." (PMID 40528196, 2025). "Interestingly, glucagon, the main counterregulatory hormone to insulin, has paracrine actions on β-cells that increase insulin secretion during states of hyperglycemia." (PMID 40013621, 2025). "However, it is important to consider that prior to experiencing hyperglycemia, individuals often exhibit increased insulin secretion." (PMID 39821966, 2025). "PP syringes were used to condition insulin at 1 IU/mL, similar to the previous case, which could be adapted for neonatal administration in cases of postnatal hyperglycaemia and hyperkalaemia." (PMID 39958972, 2025). "Therefore, this study aimed to evaluate the efficacy and safety of combining SGLT2 inhibitors with conventional intensive insulin therapy in hospitalised patients with T2DM who presented with severe hyperglycaemia." (PMID 40828947, 2025). "The findings were consistent with previous results, which showed the intervention of EUG could enhance the functionality of islet β cells, augment insulin secretion, and mitigate hyperglycemia in T1DM mice." (PMID 39792010, 2025).
Hyperglycemia (continued). "A thorough assessment of pancreatic islets and β cell function at 8 weeks of age is warranted to test the hypothesis of insufficient insulin production leading to early hyperglycemia." (PMID 40294908, 2025). "Targeted management of hyperglycemia and hypertension using insulin, metformin, labetalol, or nifedipine achieved a reduction in adverse outcome rates from 87.8% in untreated patients to 16.98% in those receiving therapy, highlighting the importance of a dual-targeted approach." (PMID 41200110, 2025). "Importantly, studies in adolescents using insulin pumps have shown that adjusting insulin delivery for protein and fat can reduce late postprandial hyperglycemia compared to carbohydrate counting alone." (PMID 41462804, 2025). "It is commonly accepted that hyperinsulinemia results from insulin resistance in glucose metabolism, which leads to hyperglycemia; this, in turn, stimulates pancreatic β-cells to release insulin to prevent more severe hyperglycemia." (PMID 41009733, 2025). "Everolimus is an mTOR inhibitor that can be used in metastatic insulinoma due to its antiproliferative activity and desirable side effect of hyperglycaemia mediated through impaired peripheral glucose uptake, impaired beta cell insulin secretion and increased hepatic gluconeogenesis." (PMID 40697399, 2025). "It is difficult to identify precise, actionable diagnostic markers or intervention targets due to the intricate and multifactorial pathophysiology of DCD, which involves a network of interrelated mechanisms (hyperglycemia, insulin resistance, vascular damage, and neuroinflammation)." (PMID 40868829, 2025). "Regarding treatment for early post-transplant hyperglycaemia, 30% exclusively use insulin." (PMID 39839808, 2025). "Insulin does not cross the placenta, but glucose does, causing fetal hyperglycemia and thereby fetal hyperinsulinemia, which probably increases fetal growth in women with GDM." (PMID 38916475, 2025). "Acquired metabolic changes, such as hyperinsulinemia, hyperglycemia, and hyperlipidemia may promote ROS production leading to mitochondrial and cell damage in insulin-sensitive tissues and cells." (PMID 39998445, 2025). "Moreover, rutin can boost the insulin release triggered by hyperglycemia in rat beta-cells while preserving their capacity to sense glucose under high glucose conditions." (PMID 40035065, 2025). "As highlighted by the nomenclature, subsets of transient and permanent NDM are distinguished by their natural history, where TNDM evolves with resolution of hyperglycemia off exogenous insulin before 18 months, only to typically recur with permanent diabetes in later life." (PMID 40979819, 2025). "In the current study, we determined the role of tau phosphorylation in brain glycolytic metabolisms by using acute hyperglycemia model and monitored the influences of human tau on insulin signaling pathway and the functions of mitochondria through comparing human tau (441 a." (PMID 40054691, 2025). "Both conditions also contribute to metabolic dysregulation, with CKD altering lipid profiles, increasing insulin resistance, and disturbing calcium-phosphorus balance, while sarcopenia reduces metabolic flexibility, worsening hyperglycemia and metabolic stress." (PMID 40095245, 2025). "In the absence of insulin, glucose cannot be effectively metabolized via the citric acid cycle, leading to ketone accumulation, hyperglycemia, osmotic diuresis, and loss of electrolytes such as sodium, potassium, and chloride." (PMID 41149081, 2025). "Regular blood glucose monitoring helps identify trends and patterns, like if a patient experiences morning hyperglycemia (the dawn phenomenon), their nighttime insulin dose may need adjustment." (PMID 40190894, 2025). "Hippocampal atrophy in T2DM may arise from chronic hyperglycemia-induced oxidative stress and impaired insulin signaling, disrupting synaptic plasticity and promoting amyloid-β deposition." (PMID 41142156, 2025).
Hyperglycemia (continued). "Conversely, reduced SIRT1 activity may worsen insulin sensitivity and contribute to the hyperglycemia observed in GDM." (PMID 39861104, 2025). "The preprandial hyperglycemia correction dose was based on a table with two columns, one for a more insulin-sensitive profile and the other for a usual profile, which could be adjusted according to the researcher’s decision." (PMID 39939862, 2025). "This may be attributed to anabolism resistance, worsening of hyperglycaemia, insulin needs, and autophagy dysfunction." (PMID 40528196, 2025). "Streptozotocin, a glucosamine–nitrosourea compound derived from Streptomyces achromogeness, induces long-term hyperglycaemia and hypoinsulinaemia in rodents via Glut2-mediated uptake into the insulin-producing beta cells, thus selectively destroying the insulin-producing cells." (PMID 40227271, 2025). "Initiatingdietary supplementation of CoQ10 in these mice reversed fasting hyperglycemia,improved glucose tolerance (by 20%), enhanced insulin sensitivity (by >2-fold), and fully restored the damage caused by pravastatin-impairedpancreatic glucose-stimulated insulin secretion by 40%." (PMID 40026529, 2025). "Patients with HNF4A mutations often show reduced glucose-stimulated insulin secretion and hypoinsulinemia-induced hyperglycemia, but without evidence of beta-cell autoimmunity, suggesting a specific dysfunction in beta-cell regulation." (PMID 40149950, 2025). "Hyperglycaemia requiring insulin infusions is common among critically ill patients." (PMID 41146739, 2025). "Additionally, Glucagon-like peptide-1 (GLP-1) exerts glucose-dependent effects by augmenting insulin secretion, inhibiting glucagon release, and supporting β-cell regeneration, thereby ameliorating hyperglycemia in T2DM patients." (PMID 40723361, 2025). "Pharmacotherapy with vitamin D3 (1000 IU/kg b.w., for 30 days), partially recovering the sensitivity of peripheral tissues to insulin, contributed to enhanced tissue utilization of glucose, which was manifested by mild compensation of hyperglycemia in animals with T2DM." (PMID 40776976, 2025). "Future studies are needed to focus on short- and long-term kidney outcomes in children with higher glucose thresholds and insulin pharmacokinetic studies are needed to define the optimal range and dose to consider treatment of hyperglycemia to reduce mortality and worse kidney outcomes." (PMID 40272476, 2025). "Akt2 knockout mice exhibited a diabetic phenotype accompanied by hyperglycemia, impaired INS action, reduced circulating leptin, and mild growth retardation, whereas Akt2 and Akt3 double knockout mice exhibited hyperinsulinemia, hyperglycemia, and reduced brain volume." (PMID 39984861, 2025). "In a separate insulin-clamp experiment, GLP-1R-deficient mice demonstrated decreased liver glycogen content, increased muscle glycogen content, and hyperglycemia during exercise compared to healthy controls, demonstrating insulin-independent effects of GLP-1 on glycolytic flux." (PMID 40722684, 2025). "It similarly induces insulin secretion in the setting of hyperglycemia." (PMID 40149944, 2025). "Prior to surgical resection, hyperglycemia may be present, and insulin infusions may be needed for glycemic control." (PMID 40385738, 2025). "This reported pericyte dysfunction supports our observations and may further stress the islet by impairing its ability to regulate blood flow in response to metabolic demands, like during hyperglycemia, potentially compromising insulin secretion." (PMID 41141358, 2025). "Furthermore, hyperglycemia increases the metabolic demand of β-cells, forcing them to consume more oxygen for insulin production and secretion." (PMID 40534855, 2025). "On the contrary, in fetuses without a GCK mutation, β-cells respond to maternal hyperglycemia with greater insulin production, which ultimately leads to the fetus’s overgrowth." (PMID 40649834, 2025).